LINC00485 (long independently transcribed non-coding RNA 485)
Gene: Long non-coding RNA gene on chromosome 12 (102,809,280 to 102,824,610, reverse strand). Ensembl gene ENSG00000258169.
Diseases named in the same sentence as LINC00485 in open-access papers:
LINC00485 is named in the same sentence as 7 diseases in open-access papers, as found by Europe PMC text mining. Sharing a sentence is not in itself a finding about the gene and the disease. The quoted sentences say what the papers report.
lung carcinoma (2 papers, 2021). "In this study, we found that the expression of Linc00485 was significantly increased in human lung cancer tissue and associated with malignant phenotypes, including tumour‐node‐metastasis (TNM) stage, metastasis and relapse." (PMID 33237626, 2021). "Taken together, this evidence suggests that Linc00485 modulates the expression of c‐Myc, thus participating in lung cancer progression." (PMID 33237626, 2021). "In a tumour xenograft animal model, the down‐regulation of Linc00485 (using short hairpin LincRNA 00485; sh‐00485) resulted in the inhibition of tumour growth of lung cancer compared with that in WT mice (n = 6 mice in each group)." (PMID 33237626, 2021). "Here, our results confirmed that up‐regulation of Linc00485 in lung cancer tumour tissues and cells facilitated lung cancer cell proliferation, migration, and invasion." (PMID 33237626, 2021). "In this study, we found that the expression of Linc00485 in lung cancer tissues was significantly higher than that in adjacent normal tissues." (PMID 33237626, 2021). "The aim of the present study was to investigate the biological function of Linc00485 in lung cancer development, thus identifying a potential target for the diagnosis and treatment of lung cancer." (PMID 33237626, 2021). "Cumulatively, these data suggest that Linc00485 functions as an miR‐298 sponge to promote c‐Myc gene expression, resulting in proliferation, migration, and invasion of lung cancer cells." (PMID 33237626, 2021). "Our findings suggested that Linc00485 silencing significantly attenuated the viability of lung cancer cells (A549, H460, and H1975) (I‐L), suppressed cell colony formation, and decreased the Ki‐67‐positive rate in A549 cells." (PMID 33237626, 2021). "We recently showed that Linc00485 was significantly up‐regulated in lung cancer tissues compared with adjacent normal tissues, and that it had a significant positive correlation with the expression of the c‐Myc oncogene." (PMID 33237626, 2021). "Linc00485 levels were associated with TNM stage in patients with lung cancer; the expression of Linc00485 was strikingly elevated in the tumour tissues of patients with stage III/IV lung cancer in comparison with those of patients with stage I/II lung cancer." (PMID 33237626, 2021). "Linc00485 is a newly discovered cancer‐related lncRNA; however, little is known about its role in lung cancer progression." (PMID 33237626, 2021). "Overall, these findings indicate that Linc00485 overexpression down‐regulates miR‐298, resulting in the up‐regulation of c‐Myc and thereby promoting the development of lung cancer." (PMID 33237626, 2021). "The Linc00485/miR‐298/c‐Myc axis is an important signalling pathway in the development of lung cancer, which may provide new insights into the pathogenesis of lung cancer and a potential target for diagnosis and treatment of lung cancer." (PMID 33237626, 2021). "In this study, we showed that the expression of Linc00485 was significantly up‐regulated in lung cancer tissues, suggesting that Linc00485 may be an oncogene." (PMID 33237626, 2021). "Moreover, in lung adenocarcinoma, Linc00485 up‐regulated the expression of cell cycle checkpoint kinase 1, thereby enhancing the resistance of lung cancer cells to chemotherapy." (PMID 33237626, 2021). "Notably, linc00485 was associated with the tumour-node-metastasis (TNM) stage in this cancer, and linc00485 overexpression increased the proliferation, migration, and invasiveness of lung cancer cells by directly sequestering miR-298, which targeted MYC." (PMID 34445233, 2021). "In addition, patients with high expression of Linc00485 had significantly shorter survival times, suggesting that Linc00485 could be used as prognostic biomarker in patients diagnosed with lung cancer." (PMID 33237626, 2021).
lung carcinoma (continued). "Although our understanding of the role of Linc00485 in lung cancer progression is still in its infancy, there is no doubt that its further study will help us to find new targets for the treatment of patients with lung cancer." (PMID 33237626, 2021). "Therefore, we speculated that the overexpression of Linc00485 elevated the expression of c‐Myc by sponging miR‐298, thereby activating multiple downstream genes including H19 and ANRIL, and thus driving lung cancer development." (PMID 33237626, 2021).
colorectal carcinoma (1 paper, 2021). A malignant epithelial neoplasm that arises from the colon or rectum and invades through the muscularis mucosa into the submucosa. "Moreover, LINC00485 overexpression significantly restricted tumor growth and liver metastasis of colorectal carcinoma in vivo." (PMID 33461166, 2021).
hepatocellular carcinoma (1 paper, 2021). A malignant tumor that arises from hepatocytes. "This study aimed to reveal the functional role of LINC00485 in hepatocellular carcinoma (HCC)." (PMID 34290977, 2021).
Uterine leiomyoma (1 paper, 2021). The presence of a leiomyoma of the uterus. "Previous studies have found that Linc00485 plays an important part in the development of uterine leiomyoma." (PMID 33237626, 2021).
cancer (3 papers, 2021). A tumor composed of atypical neoplastic, often pleomorphic cells that invade other tissues. "We found that LINC00485 expression was significantly lower in CRC tissues and cancer cells than in paired normal samples and human normal colonic epithelial cells." (PMID 33461166, 2021). "LINC00485 is downregulated in CRC tissues and cancer cells (LoVo, SW480, HCT8) compared with paired normal samples and human normal colonic epithelial cells (FHC, NCM460, CCD-18co)." (PMID 33461166, 2021).
tumour (3 papers, 2021). "We found that overexpression of LINC00485 significantly decreased tumor diameter, tumor volume at day 42, and the number of hepatic nodules in comparison to the control group, suggesting that the up-regulation of LINC00485 suppressed tumor growth and liver metastasis of CRC cells." (PMID 33461166, 2021). "Notably, silencing Linc00485 up‐regulated the expression of miR‐298 in xenograft tumour tissues compared with the control group (n = 6 mice in each group)." (PMID 33237626, 2021). "To understand the role of LINC00485 in CRC, we collected normal paracancerous tissue and tumor tissues from 52 patients with CRC." (PMID 33461166, 2021).
LINC00485 also shares sentences with these, for which no sentence is quoted: lung adenocarcinoma (1 paper).